ATM (ATM serine/threonine kinase)
Diseases named in the same sentence as ATM in open-access papers (continued):
Sharing a sentence is not in itself a finding about the gene and the disease.
cancer (continued). "Our experimental data indicated that specific inhibition of ATM catalytic activity by M3541 or M4076 extends the life of IR-induced DSBs in cancer cells." (PMID 36656721, 2023). "The recently described ATM-selective inhibitor M4076 showed synergistic activities with topotecan or irinotecan in a panel of 34 cancer cell lines." (PMID 37637936, 2023). "It has been found that the application of this ATM inhibitor effectively decreases the radiation resistance of the tumorspheres of cancer initiating cells, which are stem-like cells." (PMID 36900267, 2023). "This protective effect of ATM on cancer tumorsphere cells can be attributed to the induction of cell stress signaling networks through a mechanism mediated by ATM." (PMID 36900267, 2023). "These genes can also be used as biomarkers for resistance to pharmacological inhibition of ATM activity in cancer treatment." (PMID 37296624, 2023). "The regulation of CSCs by TGF-β depends on intrinsic signaling pathways within cancer cells, including the ATM signaling axis." (PMID 37958993, 2023). "The multiple studies of HORMAD1 function in tumors suggest a mixture of genomic protection and disruption, depending on the stage and type of cancer or additional changes in DNA repair pathways (BRCA1/2 mutation, ATM/ATR loss, and so on)." (PMID 37838177, 2023). "Ataxia Telangiectasia Mutated (ATM) protein activates CHEK2 to prevent the buildup of mutations and reduce the risk of cancer when DNA is damaged." (PMID 37732318, 2023). "First, we determined the optimal concentration of M3541 that effectively inhibits ATM function in cancer cells exposed to 5 Gy ionizing radiation by measuring ATM autophosphorylation site at serine 1981, a widely used marker for ATM activation." (PMID 36656721, 2023). "Overall, 15 patients out of 521 (2.9%) showed PVs and LPVs in five cancer-predisposing genes other than BRCA1/2 (PALB2, CHEK2, ATM, RAD51C, and RAD51D)." (PMID 37628581, 2023). "In conclusion, our study highlights the role of ATM in the maintenance of glycolytic phenotype despite functional mitochondria in oncogene-driven cancer cells since phosphorylated ATM is needed for the expression of glycolytic enzyme and OXPHOS." (PMID 37932830, 2023). "It has been shown that ATM enables the growth of mammalian adenocarcinoma stem cells, and therefore the potential benefits in cancer chemotherapy of a number of ATM inhibitors, such as KU-55933 (KU), are currently being investigated." (PMID 36900267, 2023). "In ATM-deficient lung malignancy xenografts, the combination of AZD6738 and cisplatin showed remarkable anti-cancer properties." (PMID 37062547, 2023). "In cancer cells, the ATM-Chk2 pathway is often attenuated; thus, cancer cell survival often depends on the ATR-Chk1 pathway." (PMID 36765693, 2023). "Several PARP1 inhibitors have been FDA-approved for the treatment of DNA damage repair (DDR)-deficient cancers including those harboring BRCA1/2, ATM, and RAD51C mutations." (PMID 37821462, 2023). "The Slovenian population was statistically significantly (p < 0.05) enriched for pathogenic variants in ATM, BRCA1, and CDH1 genes when compared to the gnomAD non-cancer control population." (PMID 37002323, 2023). "Functional inactivation of ATM has been observed in Ataxia-Telangiectasia (AT) patients who are prone to developing cancer, including thymic lymphoma, breast cancer, and brain cancer." (PMID 37020276, 2023). "Here we show that antibody neutralization of Gal-9, in combination with inhibition of Ataxia telangiectasia mutated (ATM), a kinase essential for DNA damage response (DDR), is a promising modality for cancer immunotherapy." (PMID 36778120, 2023).
cancer (continued). "We recently reported two new potent and selective ATM inhibitors, M3541 and M4076, that effectively sensitize cancer cells to radiation and regress human xenografts in clinically relevant animal models." (PMID 36656721, 2023). "The median age for cancer diagnosis across the BRCA1/2 mutation carriers was 46 years, in the CHEK2 group it was 42.5 years, 44.8 years for ATM, 48.6 years for PALB2, 44 years for MUTYH, and 45.6 years for BLM." (PMID 38201513, 2023). "In the JAVELIN BRCA/ATM study, a pan-cancer approach was taken, with patients selected on the presence of pathogenic BRCA1/2 or ATM alterations." (PMID 37365284, 2023). "To visualize these global relationships, we generated comprehensive heatmaps showing the efficacy and synergy responses of all 87 anti-cancer drugs screened in combination with six ATM/ATR/DNA-PK inhibitors across all 62 cell lines and 12 tissues." (PMID 38097586, 2023). "Mutation of ATM in humans can lead to a distinctive GIS, called Ataxia‐telangiectasia syndrome (ATS), in homozygous patients in addition to predisposing them to cancer." (PMID 36156462, 2023). "In MSI cancers, ATM’s intronic MS (a stretch of 15 T) shows a 4-nucleotide homozygous deletion (or hemizygous deletion + loss of heterozygosity), resulting in a decrease in the ATM protein level." (PMID 36833239, 2023). "DNA double-strand break misrepair is a potential driver of CIN and cancer predisposition as highlighted by mutations in BRCA1, ATM, NBS1 and BLM being causal in cancer syndromes associated with CIN." (PMID 36951111, 2023). "Since ATM is a major regulator of DNA repair, ATM inhibition-based therapy is under clinical trial for cancer treatment in combination with DNA damaging therapies to maximize anti-tumor efficacy." (PMID 37296624, 2023). "These patient-specific iPSC lines hold great potential for mechanistic investigations and the development of drug screening strategies aimed at addressing ATM-related cancer." (PMID 37951143, 2023). "Given its central role in DSB repair, targeting ATM for cancer therapy has garnered significant attention." (PMID 37958890, 2023). "Since histone H2AX is transiently induced upon ATM activation, this results in a heightened damage response and increases in γH2AX foci formation, which in turn result in efficient induction of cancer-cell death." (PMID 36706121, 2023). "Previously, we found that the ATM inhibitor (ATMi) KU55933 activated interferon pathways in cancer cells." (PMID 37174688, 2023). "We here combined the results from a recently published genome‐scale cancer gene discovery screen and a comprehensive description of ATM and ATR targets to identify novel regulators of the DDR with a functional role in B‐cell lymphomagenesis." (PMID 37485814, 2023). "These cancers commonly exhibit pathogenic variants in homologous recombination DNA repair genes, particularly BRCA, ATM, BARD1, RAD51 and PALB2, resulting in impaired DNA double-strand breaks (DSBs) repair." (PMID 38136266, 2023). "Collectively, the data indicate that combinatorial inhibition of APE1 and ATM can impart a synergistic lethality in the eradication of cancer cells treated with oxidative stress or IR." (PMID 36894994, 2023).
cancer (continued). "Targeting of identified HDAC, ATM, and p38 pathways shows radiosensitizing potential in cancer cells, and the clinically approved HDAC inhibitor vorinostat (SAHA) significantly improves the efficacy of TAT in vivo." (PMID 36732057, 2023). "For ATM-defective cancer cells (e.g. CLL cells), ATR becomes the main activator to regulate DNA replication stress, and inhibition of ATR can induce unrepaired DNA damage and result in the cells death." (PMID 37387166, 2023). "The ATM gene severely affects DDR; however, its deletions and mutations are known to increase the risk of cancer." (PMID 37514113, 2023). "In the last few years, the protein structure of ATM has been elucidated and hopefully there will be further insights into its function in cancer." (PMID 35008949, 2022). "For further investigations, they analysed the number of breakpoints per single chromosome and the CN-state of the ATM locus, examining public datasets of various types of cancer (lung, stomach, bladder, cervical, colon)." (PMID 35328739, 2022). "Of the patients, 73.2% underwent genetic testing, and 30% of them presented germline likely pathogenic or pathogenic variants in cancer predisposition genes (24 BRCA1, 4 BRCA2, 1 PALB2, 1 NBN, and 1 ATM)." (PMID 36531080, 2022). "Understanding the molecular and cellular regulatory mechanisms of the ATM/ATR-CHK1/CHK2 axis in human cancer cells is then essential." (PMID 36012478, 2022). "In response to the DNA damage by IR, cancer cells rapidly activate ATM, ATR, and DNA-PK, all of which are members of the phosphoinositide 3 kinase-related kinase family." (PMID 35328212, 2022). "Oxidative stress played an important roles in DNA damage and DNA damage response signaling-ATM/CHK2 pathway in cancer cell." (PMID 35148777, 2022). "Since the dysfunction of DNA repair mechanisms will deteriorate the accumulation the DNA errors and genomic instability, which is a well-known indicator of cancer, the disorder of ATM function has been a hot topic in the field of oncology." (PMID 35990964, 2022). "Since ATM connects telomere dysfunction to inflammation and cancer, an interesting possibility would be that this difference relies on zebrafish telomere biology, which is more similar to humans than to mice." (PMID 35203601, 2022). "This lower ATM activity was associated with sensitizing RYBP-expressing cells to PARP inhibitor and reducing cancer migration." (PMID 36233063, 2022). "When ATM is inhibited or inactivated in cancer cells (including colorectal, pancreatic, lung, breast, and gastric cancers), they become radiation sensitive due to defects in DNA damage repair." (PMID 36233063, 2022). "Given that the inhibition of SAC protein activities sensitizes cancer cells to chemotherapy and radiotherapy, our findings on the dual function of ATM phosphorylation make it a plausible target for radiosensitization and chemosensitization." (PMID 35085551, 2022). "Presumably, cancer cells exploit alterations of ATM/CHK2/p53to avoid cell cycle exit at the G1 phase and rely on ATR/CHK1/WEE1 activity to handle a high level of RS during continuous cell division." (PMID 36253861, 2022). "Some studies have shown that the ATM/ATR/Chk1 pathway can up-regulate PD-L1 by activating the STAT1/3-IRF1 pathway in cancer cells." (PMID 36071479, 2022). "Other genes with germline mutations had been reported to confer moderate cancer risk, such as ATM, CHECK2, and PALB2, which are also associated with other cancers." (PMID 35406420, 2022). "When cancer proneness was also reported, all the proteins concerned were found to be phosphorylation substrates of ATM." (PMID 36551628, 2022).
cancer (continued). "DSBs induced by ionizing radiation or treatment with DNA damaging agents has recently been shown to lead to an increase of PD-L1 expression in cancer cells via an ATM/ATR/Chk1-dependent mechanism." (PMID 35646698, 2022). "Of interest, the proteomic profiling of 34 SCLC cell lines demonstrated the overexpression of DDR proteins including PARP, ATR, CHK1/2 and ATM, which was shown to provide a survival advantage for cancer cells." (PMID 36358724, 2022). "Accumulating evidences from previous cancer studies highlights the repair function of ATM upon DNA double-strand breaks." (PMID 35795059, 2022). "A second germline variant was found in PALB2, CHEK2, ATM, and NBN, and they presented an additional cancer at the ages of 37, 57, 52, and 58, respectively." (PMID 36003761, 2022). "Other highly mutated HR-related genes, including RAD51B (mutation frequency in patients, 6.1%), ATR (6.1%), ATM (6.1%), PALB2 (6.1%), and BRIP1 (4.9%), have been reported to be capable of affecting the sensitivity of various cancer cells to PARPis." (PMID 35952757, 2022). "The pathogenic germline mutations of ATM play a role in DNA damage reactions and cell cycle checkpoints, so ATM has now become an important marker of cancers and a new target for cancer treatment." (PMID 36234731, 2022). "Through analysis of the Exome Aggregation Consortium cohort, excluding The Cancer Genome Atlas (TCGA), ATM germline PVs are prevalent in approximately 0.44% of the population, and higher rates are present in certain types of cancer patients." (PMID 35008949, 2022). "Recently, ATM and ATR inhibitors are highlighted as antitumor agents because numerous cancers, including CRC, utilize the ATM/ATR‐associated DDR for survival and drug resistance." (PMID 35384384, 2022). "We also show that overexpression of RYBP hinders cancer cell migration through, at least in part, ATM inhibition." (PMID 36233063, 2022). "Pathogenic/likely pathogenic variants were identified in 35% of patients in known cancer genes such as MUTYH and ATM." (PMID 36077770, 2022). "The results, however, suggest a potential role of RYBP in reducing ATM activity, and thus phosphorylation of Chk2, in two different cancer cell lines." (PMID 36233063, 2022). "Many proteins that play pivotal roles in initiating and modulating HR have been identified, including the MRN complex, breast cancer susceptibility proteins (BRCA1 and BRCA2), ATM, and ATR (ataxia telangiectasia and rad3-related)." (PMID 36207426, 2022). "ATM frequently alters in various cancers and plays a crucial role in numerous DDR-regulated cellular responses, such as DNA repair, apoptosis and cell cycle arrest." (PMID 36180906, 2022). "ATM is fully studied as an essential regulator for the proliferation, migration, and invasion of cancer cells." (PMID 35990964, 2022). "Across cancers, we found that heterozygous loss events in XPC (2/5 tumor types), POLK (4/5), LIG4 (5/5), ATM (3/5), and TP53BP1 (3/5) were common in MYBL2 High tumors." (PMID 36358918, 2022). "Due to this regulatory function and involvement in cancers, the ATM/miRNA axis has been proposed as a potential therapeutic approach for treatment of radioresistant tumors." (PMID 35408829, 2022). "After that, we compared the expression of cancer biomarkers ATM, BRCA1, PDCD1, and EGFR gene in the two groups." (PMID 36226174, 2022). "PD-L1 upregulation in cancer cells has been observed, which is also a response to DSBs, and this process requires the activation of ATM/ATR/Chk1 kinases after IR or genotoxic treatment." (PMID 35130631, 2022).
cancer (continued). "Based on the estimated overall risk for breast cancer protein-truncating variants, ATM, BRCA1, BRCA2, CHEK2 and PALB2 were identified as the major cancer susceptibility genes in the study population." (PMID 36568162, 2022). "The other way around is true too, meaning that cancers with low ERBB2 mRNA expression possess increased ATM expression, as with the colon, kidney renal clear cell and kidney renal papillary cell." (PMID 36056635, 2022). "We also observed that in the SCLC dataset, cancer gene alterations appeared to be more frequent in women, with one exception—ATM, which appears to be altered only in men." (PMID 35330454, 2022). "As an example, ZEB1, a major regulator of cancer-cell plasticity, has been identified as an ATM substrate." (PMID 35110528, 2022). "Multiple studies have shown that PD-L1 upregulation in cancer cells is ATM/ATR/Chk1-dependent and induced by IR or treatment with some DNA-damaging agents." (PMID 36497387, 2022). "For each patient, we also showed the risk in the well-known high-penetrance cancer risk alleles BRCA1 and BRCA2 with respect to other moderate-penetrance alleles including PALB2, CHEK2, ATM, BARD1, RAD51D, RAD51C and BRIP1." (PMID 35886069, 2022). "DNA damage and DNA damage response signaling-ATM/CHK2 pathway played important roles in regulation of G1/S phase transition in cancer cell." (PMID 35148777, 2022). "Altogether, the results show that chemically unrelated ligands promote autophagy in cancer cells, likely dependent on the activation of ATM and cGAS/STING pathways." (PMID 36114513, 2022). "In human sporadic cancers, somatic ATM aberrations have been frequently found using next-generation sequencing." (PMID 35628590, 2022). "The ATM-mediated DSB repair pathway in GBM cancer stem cells has also been shown to be abrogated by the ATM inhibitor KU-55933, leading to profound radiosensitization with enhancement ratios of 2.6–3.5, depending on the human GBM cell line tested." (PMID 35603818, 2022). "Ataxia telangiectasia mutated (ATM) is a key mediator of the DNA damage response, and several ATM inhibitors (ATMi) are currently undergoing early phase clinical trials for the treatment of cancer." (PMID 35962885, 2022). "Proteins implicated in HR repair pathway were frequently mutated in human cancers, such as BRCA1/2, ATM/ATR, RAD51, FA proteins, and others." (PMID 35952757, 2022). "For example ataxia-telangiectasia-mutated (ATM) and Rad3-related protein kinase (ATR) is a key regulator of the DNA damage response and ATR inhibitors are of interest to cancer researchers to potentiate the effects of radiotherapy." (PMID 35998812, 2022). "It therefore is expected that most cancer cells in those tumors will be killed by targeted drugs showing high efficacy in the background of defective ATM." (PMID 35251998, 2022). "Cisplatin was specifically chosen as adjunctive agent because of the substantial preclinical evidence for its effect in the kidney and its ease of access, as well as previous studies in cancer in combination with ATM inhibition." (PMID 36293397, 2022). "Although we find a synergistic effect between PARP inhibitor and ATM inhibitor in cancer cells, this synergy is lost in cells expressing RYBP." (PMID 36233063, 2022). "Preclinical and clinical observations demonstrated that disrupting the homologous recombination pathway, by inhibiting ATM, sensitizes cancer cells to various therapies." (PMID 36233063, 2022).